TSC1 (TSC complex subunit 1)
Diseases named in the same sentence as TSC1 in open-access papers (continued):
Sharing a sentence is not in itself a finding about the gene and the disease.
Hyperglycemia (2 papers, 2018 to 2020). An increased concentration of glucose in the blood. "Strikingly, stimulation of mTORC1 in RPTCs by deleting Tsc1 in normoglycemic mice induced tubular hypertrophy, tubular injury, and peritubular fibrosis with subsequent development of albuminuria and renal failure, thus mimicking DKD in the absence of hyperglycemia." (PMID 32726619, 2020).
ischemia (2 papers, 2020 to 2024). A hypoperfusion of the BLOOD through an organ or tissue caused by a PATHOLOGIC CONSTRICTION or obstruction of its BLOOD VESSELS, or an absence of BLOOD CIRCULATION. "However, the precise role of TSC1 in macrophages in the regulation of oxidative stress response and hepatic inflammation in liver ischemia/reperfusion injury (I/R) remains unknown." (PMID 38360839, 2024).
learning disabilities (2 papers, 2012 to 2013). "While learning disabilities have been found to vary in Tsc1 and Tsc2 mutations, social behavior was consistently impaired in two studies which employed two different TSC models." (PMID 22848848, 2012).
leiomyosarcoma (2 papers, 2022 to 2025). An uncommon, aggressive malignant smooth muscle neoplasm, usually occurring in post-menopausal women.
liver angiomyolipomas (2 papers, 2022 to 2024). "A recent retrospective analysis found that among 25 patients with liver PEComa, 88% also had renal AML, and TSC2 patients had a higher prevalence of liver PEComa than TSC1 patients (18% vs 5%; P = 0.037)." (PMID 39026968, 2024).
lung adenocarcinoma (2 papers, 2014 to 2016). A carcinoma that arises from the lung and is characterized by the presence of malignant glandular epithelial cells. "We identified several targetable pathways in EGFR/KRAS/ALK-negative lung adenocarcinoma including PI3K/mTOR signaling (TSC1, PIK3CA, AKT2), receptor tyrosine kinase signaling (ERBB4), cell cycle regulation (CHEK2, CDC27), and DNA repair (PARP4)." (PMID 24576404, 2014).
lymphopenia (2 papers, 2012 to 2014). Reduction in the number of lymphocytes. "This once again was consistent with the results obtained with mouse T cells with biallelic inactivation of Tsc1, which resulted in mTORC2 down-regulation and in peripheral T cell lymphopenia, due to the higher propensity of Tsc1KO T cells to undergo apoptotic cell death." (PMID 24633152, 2014). "As Rag1−/− mice were T/B cell deficient and might drive extensive homeostatic proliferation of naive T cells due to lymphopenia, we therefore adoptively transferred CD45.2+Tsc1 KO or CD45.2+WT naïve CD8+T cells into 4Gy-irriadiated immunocompetent CD45.1+syngeneic C57BL/6 recipients." (PMID 22363451, 2012).
Lynch syndrome (2 papers, 2016 to 2019). An autosomal dominant hereditary neoplastic syndrome characterized by the development of colorectal carcinoma and a high risk of developing endometrial carcinoma, gastric carcinoma, ovarian carcinoma, renal pelvis carcinoma, and small intestinal carcinoma.
macrocytic anaemia (2 papers, 2014 to 2019). "Conversely, constitutive activation of mTORC1 (Vav-TSC1 KO) leads to macrocytic anaemia with larger reticulocytes and RBCs with elevated Hb levels." (PMID 31729420, 2019). "We further showed that activation of mTORC1 by deletion of Tsc1 results in severe macrocytic anemia, while genetic inhibition of mTORC1 results in a lethal microcytic anemia." (PMID 25201874, 2014).
mesenchymal tumors (2 papers, 2022 to 2023). "We also compared the protein level data and found that PI3K pathway activators like TSC1, 4EBP1 and p4EBP1, PI3K-p85, RICTOR-pT1135 were significantly increased in high mesenchymal tumors, and PI3K inhibitor like LKB1 and INPP4B expression was significantly decreased." (PMID 36120580, 2022).
metastatic disease (2 papers, 2020 to 2024). "The high frequency of mutations in the genes RB1, TSC1 and FOXA1 in the metastatic samples with few or no concordant cases also suggests these genes are similarly relevant to the biology of metastatic disease." (PMID 32811538, 2020).
microcephaly (2 papers, 2021). A congenital or acquired developmental disorder in which the circumference of the head is smaller than normal for the person's age and sex. "Knockout of Raptor or mTOR in the developing brain causes microcephaly, reduced neural progenitor proliferation and postnatal lethality, while knockout of Tsc1 or Tsc2 causes macrocephaly and premature neural progenitor differentiation." (PMID 34381067, 2021).
multiple endocrine neoplasia (2 papers, 2020 to 2023). Multiple endocrine neoplasia (MEN) is a group of rare inherited cancer syndromes characterized by the development of two or more endocrine gland tumors, sometimes with tumor development in other tissues or organs. "Furthermore, although the majority of NETs are sporadic tumors, a proportion of them (10–15%) are attributable to familial cancer syndrome, like Multiple Endocrine Neoplasia (MEN) 1 and 2, von-Hippler-Lindau Syndrome and Tuberous Sclerosis Complex 1 (TSC-1) and Tuberous Sclerosis Complex 2 (TSC-2)." (PMID 32397669, 2020).
neuroendocrine tumors (2 papers, 2015 to 2022). "Although both somatic TSC1 mutation and mTOR mutations have been reported in exceptional responders, these alterations are relatively rare in tumor types such as hormone–receptor positive breast cancer and neuroendocrine tumors, where rapalogs are commonly used." (PMID 25944619, 2015).
osteoporosis (2 papers, 2019). A condition of reduced bone mass, with decreased cortical thickness and a decrease in the number and size of the trabeculae of cancellous bone (but normal chemical composition), resulting in increased fracture incidence. "To test this hypothesis, we investigated the possibility of the involvement of Hamartin (Tsc1) expressed by osteoclasts in the pathogenesis of osteoporosis mouse model using GST–RANKL fusion protein injections." (PMID 31263418, 2019). "The deletion of Tsc1 in osteoclast lineage cells in mice prevented bone resorption and bone loss in a RANKL-induced mouse model of osteoporosis, although neither bone volume nor osteoclastic parameter was markedly altered in these knockout mice under physiological conditions." (PMID 31263418, 2019). "Interestingly, we have found that deletion of TSC1 in murine B cells produces constitutive activation of mTORC1 and stimulates RANKL but represses OPG expression via negative regulation of AKT and β-catenin and subsequently promotes osteoclast formation and generates osteoporosis in mice." (PMID 31088250, 2019).
Parkinson disease (2 papers, 2018 to 2021). A progressive degenerative disorder of the central nervous system characterized by loss of dopamine producing neurons in the substantia nigra and the presence of Lewy bodies in the substantia nigra and locus coeruleus. "According to previous studies, Th17 cells can infiltrate the brains of patients of Parkinson’s disease and induce neuronal cell death, and Tsc1 deficiency affects T cell development and function." (PMID 33957945, 2021).
renal failure (2 papers, 2020 to 2022). "The loss of functioning parenchymal tissue in the kidneys of Tsc1 KO mice can interfere with renal function and lead to renal failure, a condition that is also associated with aberrant amino acid catabolism." (PMID 36142537, 2022). "However, based on our published studies, indicating the maintenance of normal renal function in Tsc1 KO mice, the role of renal failure in the reduction in amino acids would be at best minimal." (PMID 36142537, 2022). "Homozygous Tsc1 KO in RPTCs increased albuminuria and urinary KIM-1 excretion and induced renal failure." (PMID 32726619, 2020).
retina degeneration (2 papers, 2016 to 2021). "In 7-month-old Tsc1-cKO mice, activated microglial cells were found in the subretinal space, a phenomenon which was a hallmark of retina degeneration." (PMID 34777691, 2021). "To study the long-term effect of Tsc1 loss in cones of mice with retinal degeneration, we first analyzed the effect of its loss in wild-type mice." (PMID 27362797, 2016). "Our results suggested that in adult Tsc1-cKO mice, mTORC1 activation accelerated senescence of the postmitotic, fully differentiated neuroretinal cells and ultimately led to retinal degeneration." (PMID 34777691, 2021). "Finally, we showed that the Tsc1-cKO mice represented an animal model of retinal degeneration and aging." (PMID 34777691, 2021).
retinoblastoma (2 papers, 2015 to 2022). A malignant tumor that originates in the nuclear layer of the retina. "Both intrinsic subtypes are associated with distinct genomic alterations like FGFR3and TSC1 mutations in the luminal and retinoblastoma (RB) alteration in the basal subtype." (PMID 26316886, 2015).
sarcopenia (2 papers, 2022 to 2023). Progressive decline in muscle mass due to aging which results in decreased functional capacity of muscles. "Mice with myofiber‐specific knockout of TSC1 (TSC1mKO), in which mTORC1 is hyperactivated in fully differentiated myofibers, were used as a mouse model of sarcopenia." (PMID 36398408, 2023). "Consistently, myofiber‐restricted inactivation of TSC1 leads to sustained mTORC1 activity (TSC1mKO mice) and accelerates the development of sarcopenia in adult mice." (PMID 36398408, 2023). "Genetic activation of mTORC1 by conditionally ablating mTORC1 upstream inhibitor TSC1 in skeletal muscle accelerates sarcopenia development in adult mice." (PMID 36398408, 2023). "Consistent with the early‐onset sarcopenia developed in myofiber‐specific knockout of TSC1 (TSC1mKO) mice, multiple lines of evidence indicate chronic up‐regulation of mTORC1 signalling in the muscle of aged mice and humans." (PMID 36398408, 2023).
scoliosis (2 papers, 2020 to 2021). A congenital or acquired spinal deformity characterized by lateral curvature of the spine. "These rare manifestations were more commonly observed in adults than children (66.2% vs. 22.7%), in females versus males (58.4% vs. 41.6%; except for scoliosis: 48.9% vs. 51.1%), and in those with TSC2 versus TSC1 (67.0% vs. 21.1%; except for thyroid adenoma: 42.9% vs. 57.1%)." (PMID 34229737, 2021).
Stroke (2 papers, 2021 to 2023). Sudden impairment of blood flow to a part of the brain due to occlusion or rupture of an artery to the brain. "Apart from pathogenic or likely pathogenic findings, 41 rare VUS in 325 stroke-related candidate genes were detected in 39 probands, including eight novel variants: ABCA1 p.H1223P, ACTA2 p.N298S, COL5A1 p.P930R, FBN1 p.Q514E, FBN1 p.K1052T, GP1BA p.P437*, RNF213 p.N1631Efs*34, and TSC1 p.P397del." (PMID 36580209, 2023).
type 2 diabetes (2 papers, 2019 to 2020). "In conclusion, this study indicates a potential therapeutic effect of metformin on Tsc1 deletion-induced kidney pathology, although currently metformin is primarily prescribed to treat patients with type 2 diabetes." (PMID 32566257, 2020).
Wilms tumor (2 papers, 2017 to 2022). An embryonal neoplasm characterized by the presence of epithelial, mesenchymal, and blastema components. "Thepatient with Wilms tumors had a fragment deletion of TSC1.Fifty-three patients showed TSC2 gene mutations." (PMID 35638823, 2022). "The WT1 gene, a TSG often mutated in pediatric Wilms’ tumor, was also down-regulated in TSC1/2-one-hit cells." (PMID 27682873, 2017).
acne (1 paper, 2025). An inflammatory process of the sebaceous glands which is characterized by comedones, nodules, papules and/or pustules on the skin. "We hypothesize that upregulation of TSC1 may serve as a self-protective mechanism in severe acne." (PMID 40860874, 2025).
ameloblastoma (1 paper, 2021). The most common odontogenic tumor, arising from the epithelial component of the embryonic tooth and usually affecting the molar-ramus region of the mandible or maxilla. "One article reported 45% of their cohort (9/20 ameloblastomas) to harbor missense mutations (in non-SNP sites) affecting TSC1." (PMID 35048068, 2021).
amyotrophic lateral sclerosis (1 paper, 2023). Amyotrophic lateral sclerosis (ALS) is a neurodegenerative disease characterized by progressive muscular paralysis reflecting degeneration of motor neurons in the primary motor cortex, corticospinal tracts, brainstem and spinal cord. "miR-193b-3p is significantly downregulated in patients with amyotrophic lateral sclerosis (ALS) and downregulation of miR-193b-3p promotes autophagy and cell survival by targeting TSC1/mTOR signaling." (PMID 36824367, 2023).
asthma (1 paper, 2017). "Nevertheless, the results in our study are quite consistent compared with the uncertain effect of rapamycin on asthma in some previous studies, but are highly consistent with the effect of TSC1-KO macrophages in asthmatic mice." (PMID 28225024, 2017).
Ataxia (1 paper, 2018). Ataxia refers to impaired coordination of voluntary muscle movement. "As a yardstick of the full scale of cerebellum-specific impairment of gait, we used Purkinje cell-specific Tsc1-/- mice, which show cerebellar degeneration and ataxia; L7Cre;Tsc1flox/flox)." (PMID 30226467, 2018).
autoimmune disorders (1 paper, 2017). "Instead, we found that specific depletion of Tsc1 in DCs resulted in the development of splenomegaly and lymphadenopathy, increased serum immunoglobulin levels and body weight loss in mice, which were characteristics of spontaneous autoimmunity." (PMID 28079897, 2017). "Furthermore, serum levels of IgG1 and IgE in CD11cCreTsc1f/f mice were higher than in WT mice, indicating a role of Tsc1 in autoimmune disorders." (PMID 28079897, 2017).
bipolar disorder (1 paper, 2016). A disorder of the brain that causes unusual shifts in mood, energy, activity levels and the ability to carry out day-to-day tasks. "TSC1 has also been implicated in bipolar disorder, without attaining genome-wide significance." (PMID 27499730, 2016).
brain malformations (1 paper, 2019). "It is known that activating the mTOR pathway causes the epileptogenicity of brain malformations, specifically FCD, TS, and HS, which is supported by our finding that 80% of APEs with TSC1 or TSC2 variants had such malformations." (PMID 31875159, 2019). "Eight of ten APEs (80%) with TSC1 or TSC2 variants but none of the three APEs with DEPDC5 variants had brain malformations including FCD, HS, or TS." (PMID 31875159, 2019).
carcinosarcoma (1 paper, 2024). A malignant tumor composed of a mixture of carcinomatous and sarcomatous elements. "While the ILC and carcinosarcoma were noted to share mutations in NOTCH1 (c.6685G>A) and TSC1 (c.2647G>A) we were unable to send paired normal samples and it is possible that these VUS could be germline mutations explaining the expression within both tumors." (PMID 39076998, 2024). "Among variants of unknown significance (VUS), two were identified in both carcinosarcoma and ILC samples with approximately 50% VAF, including NOTCH1 (c.6685G>A, p.V229M, VAF 60.6% carcinosarcoma, 48.1% lobular) and TSC1 (c.2647G>A, p.A883T, VAF 58.5% carcinosarcoma, 40.9% lobular)." (PMID 39076998, 2024).
Carney syndrome (1 paper, 2022).
cerebral cortical dysplasia (1 paper, 2022). Abnormalities in the development of the cerebral cortex. "The areas of cerebral cortical dysplasia in the form of cortical tubers (CT) were prevalent in 42% and 80% of TSC1 and TSC2 patients, respectively." (PMID 35440050, 2022).
cervical cancer (1 paper, 2013). A primary or metastatic malignant neoplasm involving the cervix. "Moreover, TSC1 also has anti-proliferative effects on human cervical cancer (HeLa) cells." (PMID 23355874, 2013).
cholangiocarcinoma (1 paper, 2025). A carcinoma that arises from the intrahepatic biliary tree (intrahepatic cholangiocarcinoma) or from the junction, or adjacent to the junction, of the right and left hepatic ducts (hilar cholangiocarcinoma). "A notable case report highlighted a dramatic response to mTOR-targeted therapy in a patient with intrahepatic cholangiocarcinoma harboring TSC1 and ARID1A mutations, indicating potential oncogenic dependence on mTOR in certain subtypes." (PMID 41300430, 2025).
Cholestatic liver disease (1 paper, 2020). "Cholestatic liver diseases result from a repeated exposure to unconjugated primary biliary acids, which may activate mTOR through the IκB kinase β (IKKβ)/Tuberous sclerosis 1 (TSC1)/mTOR pathway as demonstrated in some precancerous conditions such as Barrett’s esophagus." (PMID 32070029, 2020).
chronic pancreatitis (1 paper, 2022). A chronic inflammatory process causing damage and fibrosis of the pancreatic parenchyma. "We also demonstrate that the protective role of miR-301a deletion in chronic pancreatitis and PanIN is dependent on two downstream axes: Tsc1/mTOR and Gadd45g/Stat3." (PMID 35211358, 2022). "Here, we measured Tsc1 expression in both chronic pancreatitis and PanIN mice models." (PMID 35211358, 2022).
clear cell carcinomas (1 paper, 2019). "FAM129A expression was detected in Tsc1 and Tsc2 knockout mice, in sporadic human RCC including clear cell carcinomas, granular cell carcinomas and spindle cell carcinomas." (PMID 31016032, 2019).
cognitive decline (1 paper, 2025). "Causative or predisposing variants have been linked to altered PI3K signaling with increased risk of cognitive decline in PIK3CD, AKT3, and TSC1/2." (PMID 40806341, 2025).
colorectal tumor (1 paper, 2025). "The functional impact of TSC1-mediated regulation of sialylation was further validated in our in vivo colorectal tumor models." (PMID 41445741, 2025).
communication disorder (1 paper, 2022). A disorder characterized by an individual's inability to comprehend or share ideas or feelings because of an impairment in language, speech, or hearing. "Furthermore, a significant difference was found between the presentation of communication disorders in TSC1 and TSC2 at a prevalence of 6% and 50%, respectively (Z = −3.17, df = 1, p = 0.0015)." (PMID 35440050, 2022).
congenital heart defects (1 paper, 2022). "This study marks the first empirical investigation of the co-morbidity between congenital heart defects (CHD), NDDs, and KDs in TSC1 and TSC2 patients." (PMID 35440050, 2022).
Cortical tubers (1 paper, 2023). Cortical tubers in the brain are hamartomatous lesions typically located at the gray-white matter interface, commonly in the frontal and parietal lobes. "In 2020, Feliciano suggested that a loss of both functional copies of TSC1 or TSC2 is perhaps not necessary to cause TSC and that haploinsufficiency or dominant negative mutations could also underlie the pathogenesis of cortical tubers." (PMID 37232723, 2023).
dementia (1 paper, 2022). Loss of intellectual abilities interfering with an individual's social and occupational functions. "Prior research has suggested that TSC1/2 mutations, excessive mTOR signaling, and dementias may be linked mechanistically." (PMID 35241183, 2022).
diabetic nephropathy (1 paper, 2020). "Additionally, podocyte-specific Tsc1 knockout mice show features of diabetic nephropathy and mTORC1 hyperactivation is present in podocytes of patients with diabetic nephropathy." (PMID 32191726, 2020).